Y_RNA (Y RNA )
Gene: Miscellaneous RNA gene on chromosome 17 (50,696,644 to 50,696,760, forward strand). Ensembl gene ENSG00000201340.
Homologues: Orthologues: chimpanzee Y_RNA (100% identical), macaque Y_RNA (97% identical). Paralogues in human: Y_RNA (74% identical), Y_RNA (73% identical), Y_RNA (72% identical), RNY3 (71% identical), Y_RNA (71% identical), RNY3P1 (70% identical), RNY3P16 (70% identical), Y_RNA (70% identical), RNY3P7 (69% identical), RNY3P9 (69% identical), Y_RNA (69% identical), RNY3P14 (68% identical), and 86 more.